SMAD7 (SMAD family member 7)
Diseases named in the same sentence as SMAD7 in open-access papers (continued):
Sharing a sentence is not in itself a finding about the gene and the disease.
colorectal cancer (56 papers, 2008 to 2025). A primary or metastatic malignant neoplasm that affects the colon or rectum. "Our study focused on examining the impact of the SMAD7 gene variant rs4939827 on the risk of colorectal cancer occurrence." (PMID 38275467, 2024). "Yan X and colleagues have shown that the TGF-β signaling pathway is impaired due to SMAD7, leading to an increased risk of colorectal cancer." (PMID 38275467, 2024). "The findings of our research indicate a correlation between variants of the SMAD7 gene and the likelihood of developing colorectal cancer in our study population." (PMID 38275467, 2024). "In this research, a case–control study was conducted to evaluate the association between the SMAD7 gene variant rs4939827 and the risk of colorectal cancer in the western Romanian population." (PMID 38275467, 2024). "Despite the extensive research on the correlation between SMAD7 polymorphisms and colorectal cancer (CRC), the conclusions of studies are still contradictory." (PMID 36607878, 2023). "In a previous G×BMI analysis, we observed a locus located within SMAD7 that interacts with BMI on colorectal cancer risk." (PMID 37249599, 2023). "TGFβ in cellular proliferation and inflammation has been proposed as a mechanism of action through which SMAD7 interacts with colorectal cancer risk." (PMID 37249599, 2023). "SMAD7 rs4939827 in the recessive and co-dominant models was associated with colorectal cancer risk [TT/CT + CC: OR = 2.90, 95%CI (1.38–6.09), p = 0.005; CC + TT/CT: OR = 1.66, 95%CI (1.00–2.75), p = 0.01]." (PMID 35016683, 2022). "In the present study, we conducted a case–control study to investigate the potential association of SMAD7 gene polymorphisms with the risk of colorectal cancer in an Iranian population." (PMID 35016683, 2022). "In colorectal cancer, SMAD7 expression was associated with poorly differentiated cell morphology, higher cell proliferation, and liver metastases." (PMID 35912252, 2022). "A relationship between the CASC8, SMAD7 genes, and risk of colorectal cancer were analyzed in a meta-analysis including 90 studies (168,471 cases and 163,223 controls)." (PMID 32582694, 2020). "The study by Kirac showed that rs4939827 polymorphism of the SMAD-7 gene is associated with developing colorectal cancer in a Croatian population." (PMID 32856881, 2020). "Smad7 has previously been found to be amplified in colorectal carcinoma, and this event is linked to poor prognosis for these patients." (PMID 32888405, 2020). "The SMAD7 SNP rs4939827, identified as a colorectal cancer risk SNP was the most significantly associated SNP in our breast-colorectal data (P = 1.85E-04) with a consistent direction of association for the risk allele (T)." (PMID 29698419, 2018). "There is an important role of SMAD7 gene in colorectal cancer as the allele C is protective against this disease." (PMID 29084532, 2017). "The objective of our investigation is to study the relationship between the rs4939827 SNP in the SMAD7 gene, Mediterranean diet pattern and the risk of colorectal cancer." (PMID 29084532, 2017). "A genome-wide association study identified a common genetic variant rs4939827 at 18q21 in SMAD7 to be related with colorectal cancer (CRC) risk with OR=1.2 and P =7.80E-28." (PMID 28467803, 2017). "A number of studies have reported that SMAD7 polymorphisms (rs4464148, rs4939827, and rs12953717) are associated with colorectal cancer (CRC) risk, but the results from these studies remain conflicting." (PMID 28070019, 2016). "In support of this notion, Smad7 overexpression is associated with poor prognosis in colorectal cancer." (PMID 25566830, 2015). "Regarding to the recent genome-wide scan, a risk locus for colorectal cancer at 18q21 has been found, which maps to the SMAD7 gene." (PMID 25289133, 2014). "Recently, genome-wide studies have recognized the SMAD7 gene (18q21) as an associated modest locus but highly significant increase in colorectal cancer risk." (PMID 25289133, 2014).
colorectal cancer (continued). "In the subgroup analysis by cancer types, SMAD7 rs12953717 polymorphism was significantly associated with colorectal cancer." (PMID 23472153, 2013). "Recent genome-wide studies identified a risk locus for colorectal cancer at 18q21, which maps to the SMAD7 gene." (PMID 23560096, 2013). "In summary, using data from the Colorectal Cancer Family Registry, we confirmed the association between SMAD7 and CRC found in GWAS." (PMID 23560096, 2013). "Perturbation of SMAD7 expression has been previously documented to influence colorectal cancer progression, and loss of chromosome 18q21 encompassing SMAD7 is common in colorectal cancer." (PMID 23472153, 2013). "As the number of copies of SMAD7 increases, the risk of colorectal cancer increases for carriers and the prognosis is worsened for patients with colorectal cancer." (PMID 23472153, 2013). "Study results showed that lower median SMAD7 mRNA expression was associated with colorectal cancer risk allele at rs12953717." (PMID 23472153, 2013). "Our objective was to confirm the association between SMAD7 SNPs and colorectal cancer risk in the multi-center Colon Cancer Family Registry." (PMID 23560096, 2013). "In this study we found a significant association between SMAD7 variant rs4939827 (18q21.1) and risk of colorectal cancer in Croatian population." (PMID 24066093, 2013). "A polymorphism in the human SMAD7 gene (NM_005904) associated with increased risk of developing colorectal carcinoma (rs4939827) was used as a model system to study the performance of rhPCR for SNP discrimination with genomic DNA." (PMID 21831278, 2011). "Smad4 mutation and its reduced level in colorectal cancer are directly correlated to poor prognosis and increased metastasis, whereas Smad7 expression is associated with poor outcome in gastric carcinomas." (PMID 18781153, 2008). "As a result, rs4939827 SNP in SMAD7 and miR-375 might be considered as early diagnostic or prognostic biomarkers of colorectal cancer." (PMID 35330456, 2022). "Based on the identified association of SMAD7 gene variations and haplotypes with colorectal cancer risk in our population, genetic variations in this gene region may have a role in CRC development." (PMID 35016683, 2022). "However, concerning other cancers, in line with the present study, research on colorectal cancer in Caucasian and Asian populations, stomach and lung cancers in a western population has also shown that SMAD-7 gene is associated with developing cancer." (PMID 32856881, 2020). "In this paper, we set out to investigate the role of one polymorphisms of SMAD7: rs2337104 on colorectal cancer risk based on hypothesis that there may be the association between that SNP and colorectal cancer in an Iranian population." (PMID 25289133, 2014). "Regardless the complex role of SMAD7 as an intracellular mediator of TGF-b type 1 receptor in cancer development, the relevance of several genetic variants such as single nucleotide polymorphism (SNP) of SMAD7 with colorectal cancer has been proved by some studies (18,-)." (PMID 25289133, 2014). "Our results indicated that we couldn’t recommend the SMAD7 gene to be associated with progression or metastasis of colorectal cancer in an Iranian population." (PMID 25289133, 2014). "Colorectal cancer risk associated with haplotypes formed by SMAD7 SNPs rs12953717 and rs11874392." (PMID 23560096, 2013). "SMAD7 SNPs were associated with colorectal cancer risk in the Colon Cancer Family Registry." (PMID 23560096, 2013). "SMAD7 tagging SNPs and colorectal cancer risk in the Colon Cancer Family Registry." (PMID 23560096, 2013). "Hence, allele-specific expression of SMAD7 is likely to be the biological basis for colorectal cancer predisposition associated with 18q21 variation." (PMID 23472153, 2013). "Indeed, genomic approaches identified specific SMAD7 alleles that impact colorectal cancer risk." (PMID 29799477, 2018).
colorectal cancer (continued). "The SMAD7 gene and specifically the allele C could be protective for colorectal cancer." (PMID 29084532, 2017). "Colorectal cancer (CRC) cells express high SMAD7, a protein involved in the control of CRC cell growth." (PMID 39001432, 2024). "Colorectal cancer (CRC) cells are characterized by high levels of SMAD7, a protein involved in the positive control of growth and survival of cancer cells." (PMID 39001432, 2024). "Our current analytical strategy excluded SMAD7 and other known GWAS loci for colorectal cancer and BMI." (PMID 37249599, 2023). "ALKBH1‐mediated m1A demethylation of METTL3 mRNA promotes the metastasis of colorectal cancer by downregulating SMAD7 expression." (PMID 36550779, 2023). "In colorectal cancer, SMAD7 protein expression is increased and its overexpression is negatively correlated with the survival rate of colorectal cancer patients." (PMID 34254453, 2021). "Smad7, as a tumor suppressor gene, is low expressed in various cancers, including colorectal cancer." (PMID 34775378, 2021). "Genome-wide association studies (GWAS) have identified 18q21 as a risk locus for colorectal cancer (CRC), which maps to the SMAD7 gene." (PMID 32190221, 2020). "SMAD7 protein levels are markedly upregulated in human colorectal cancer relative to matched adjacent tissues similar to findings in colorectal cancer cell lines." (PMID 29799477, 2018). "In contrast, Smad7 has been shown to inhibit cancer progression and metastasis in many tumor types in experimental models, including melanoma, breast cancer colorectal cancer, head and neck and liver cancers in vitro and in vivo." (PMID 25566830, 2015). "A common genetic variant, rs4939827, located in SMAD7, was identified by two recent genome-wide association (GWA) studies to be strongly associated with the risk of colorectal cancer (CRC)." (PMID 22457752, 2012). "In this report, we show that ectopic expression of Smad7 enhances colorectal cancer metastasis to liver in a splenic injection model." (PMID 18781153, 2008). "Circ-SMAD7 has been revealed to be down-regulated in colorectal cancer tissues, and overexpression of circ-SMAD7 repressed the migration and invasion via inhibiting epithelial-to-mesenchymal transition in colorectal cancer cells." (PMID 34507559, 2021). "Previous studies reported Smad7/TGFβ-mediated metastasis in various types of tumors, including colorectal cancer, indicating that miR-581 could be a novel regulator of metastasis." (PMID 32899503, 2020). "Interestingly, seven of the shared significant genes have been associated to colorectal cancers, including UTP23, GREM1, SCG5, SMAD7, CABLES2, LAMA5, and PREX1." (PMID 32245788, 2020). "However, other studies have reported a dual role of Smad7 expression in colorectal cancer, in line with the dual role of TGF-β in other cancer types." (PMID 32888405, 2020). "Moreover, knockdown of Smad7 expression in a human colorectal carcinoma xenograft model has been shown to reduce tumor growth in vivo, giving further evidence for a tumor-promoting role of Smad7 in colorectal cancer." (PMID 32888405, 2020). "The mechanism by which rs4939827 may influence colorectal cancer involves inhibitory role of the SMAD7 protein in the transforming growth factor beta (TGF-β) signalling pathway." (PMID 24066093, 2013). "Furthermore, upregulation of Smad7 in colorectal cancer has been correlated with poor survival." (PMID 18781153, 2008). "For example, in colorectal cancer, ALKBH1‐mediated m1A demethylation of METTL3 mRNA promotes metastasis by downregulating SMAD7 expression." (PMID 41017026, 2025). "Colorectal cancer (CRC) cells contain elevated levels of Stat3 and Smad7, two proteins involved in the growth and survival of neoplastic cells." (PMID 36291778, 2022).
colorectal cancer (continued). "GRAIL analysis revealed 19 regions with a significant score, including the strongest connections with TGF-β signalling pathway genes such as TGFB1, SMAD7 and BMP4, thus suggesting a pivotal role of this pathway in colorectal cancer development." (PMID 27145994, 2016). "Thus, Smad7 could be a potential target for therapeutic intervention of colorectal cancers." (PMID 18781153, 2008). "Smad7 not only blocks TGF-β-mediated antitumour function, but also promotes tumour progression and metastasis of colorectal cancer probably through the cooperation with oncogenic Ras." (PMID 18781153, 2008). "For example, hsa-miR-425-5p may promote tumor occurrence and metastasis by activating CTNND1 related pathway, hsa-miR-186-5p regulates TGFβ signaling pathway through expression suppression of SMAD7 and SMAD6 genes in colorectal cancer." (PMID 36561136, 2022). "Notably, a correlation between expression of Smad7 mRNA and both c-Jun and HDAC6 mRNA can also be seen in clinical material from patients with colorectal carcinoma, and high levels of HDAC6 mRNA correlate with poor survival." (PMID 32888405, 2020). "The identified connections showed that there was a higher-than-expected degree of connectivity, with a significance of PGRAIL<0.05 being observed for TGFB1, SMAD7 and BMP4. rs2238126 in ETV6 presented a weaker than expected connection with other genes reported in previous GWAS of colorectal cancer." (PMID 27145994, 2016). "SMAD7 expression was significantly different (p value < 0.05) across all three survival metrics, with an HR > 1 for OS and RFS and an HR < 1 for PPS, suggesting a complex relationship between its expression levels and colorectal cancer patient outcomes that warrants further investigation." (PMID 41144378, 2025). "Since miRNA-638 has been reported to be down-regulated to promote apoptosis and autophagy by Rh2 in several cancer cell types, other miRNAs may also be involved in the development of colorectal cancers, such as TGFBR1:miR-532-5P, SMAD7:miR-375, PI3KCA:miR-520a, and CD44:miR-509-3P." (PMID 37764996, 2023).
pulmonary fibrosis (53 papers, 2005 to 2026). Chronic progressive interstitial lung disorder characterized by the replacement of the lung tissue by connective tissue, leading to progressive dyspnea, respiratory failure, or right heart failure. "After adenovector-mediated Smad7 gene transfer in fibrotic mice lung, stimulation of Smad7 mRNA expression caused the reduction of pulmonary fibrosis in the mice." (PMID 32552754, 2020). "In addition, they demonstrated that OGG1 deficiency relieved pulmonary fibrosis and decreased the expression of Smad7 and phosphorylation of SMAD2/3 in bleomycin‐treated mice." (PMID 36788635, 2023). "In a murine model of idiopathic pulmonary fibrosis (IPF), transient gene transfer of Smad7 significantly attenuated bleomycin-induced lung fibrosis by blocking TGF-β-mediated signaling and myofibroblast activation." (PMID 40745212, 2025). "HDAC6 has been shown to upregulate the TGF‐β1‐Smad2/3 and ‐Smad7 signalling pathways, leading to renal and pulmonary fibrosis." (PMID 39232846, 2024). "In smoking-induced pulmonary fibrosis, circRNA_0026344 was shown to target exosomal miR-21 to activate SMAD7, which involves abnormal crosstalk between epithelial cells and fibroblasts." (PMID 38460002, 2024). "Epigenetic modification on K70 of SMAD7 by SETD7-mediated methylation decreases the protein stability of SMAD7 by ubiquitination-dependent manner via Arkadia E3 ligase in mouse models of pulmonary fibrosis." (PMID 35812730, 2022). "YX-2102 ameliorated lung fibrosis by suppressing EMT in a CB2R dependent manner via regulation of the Nrf2/Smad7 pathway, indicating that CB2R is a potential therapeutic target for PF treatment." (PMID 36474298, 2022). "When they developed functional studies with the mice bleomycin-treated model, miR-877-3p sequestration inhibited the differentiation of LR-MSC to myofibroblasts and attenuated pulmonary fibrosis by its effect on Smad7." (PMID 35743055, 2022). "On the contrary, Smad7 inhibits pulmonary fibrosis by competitively binding to TGF-β and its receptors complex with Smad3." (PMID 33953686, 2021). "Further, miR-21 has been shown to play multiple roles in different pulmonary diseases, such as idiopathic pulmonary fibrosis and pulmonary arterial hypertension, by targeting several immune receptors and cytokines, including IL-12 and SMAD7." (PMID 28856588, 2017). "We found that miR-877-3p sequestration inhibited the myofibroblast differentiation of LR-MSC and attenuates bleomycin-induced lung fibrosis by targeting Smad7." (PMID 27444321, 2016). "After transfection of LV-miR-877-3p-inhibitor, the expression of Smad7 was increased in the bleomycin-induced mouse pulmonary fibrosis model, and the development of pulmonary fibrosis was profoundly restrained." (PMID 27444321, 2016). "Inhibiting miR-21 expression in the lung successfully ameliorated pulmonary fibrosis and it was suggested that miR-21 promoted fibrosis by targeting the anti-fibrotic protein Smad7." (PMID 26758514, 2016). "More importantly, we found that miR-877-3p sequestration inhibited the myofibroblast differentiation of LR-MSCs and attenuates bleomycin-induced lung fibrosis by targeting Smad7." (PMID 27444321, 2016). "Transient gene transfer and expression of Smad7, introduced by recombinant human type 5 adenovirus vector into the lungs, prevented pulmonary fibrosis induced by bleomycin in mice." (PMID 20628605, 2010). "Recently, Smad7, an intracellular antagonist of TGFβ signaling, has been shown to attenuate bleomycin-induced lung fibrosis in mice receiving intratracheal injection of recombinant adenovirus overexpressing Smad7." (PMID 15949035, 2005). "Thus, we demonstrated that MSCs play a role in the treatment of BLM-induced pulmonary fibrosis through the TGF-β1/Smad7 pathway and that MSCs overexpressing DCN showed better efficacy." (PMID 40438789, 2025).